UBE2T (ubiquitin conjugating enzyme E2 T)
Description:
Accepts ubiquitin from the E1 complex and catalyzes its covalent attachment to other proteins. Catalyzes monoubiquitination. Involved in mitomycin-C (MMC)-induced DNA repair. Acts as a specific E2 ubiquitin-conjugating enzyme for the Fanconi anemia complex by associating with E3 ubiquitin-protein ligase FANCL and catalyzing monoubiquitination of FANCD2, a key step in the DNA damage pathway. Also mediates monoubiquitination of FANCL and FANCI. May contribute to ubiquitination and degradation of BRCA1. In vitro able to promote polyubiquitination using all 7 ubiquitin Lys residues, but may prefer 'Lys-11'-, 'Lys-27'-, 'Lys-48'- and 'Lys-63'-linked polyubiquitination.
Synonyms: HSPC150; PIG50; FANCT
Tractability: Small molecule: a structure with a bound ligand is known; it has a binding pocket of medium quality. PROTAC: UniProt records ubiquitination sites on it; ubiquitination databases record sites on it.
Target class: Enzyme; Transferase
Gene: Protein-coding gene on chromosome 1 (202,328,714 to 202,341,984, reverse strand). Ensembl gene ENSG00000077152.
Subcellular location: Nucleus
Subcellular location (Human Protein Atlas): Nucleoli; Nucleoplasm
Pathways (Reactome):
DNA Repair: Fanconi Anemia Pathway
Metabolism of proteins: Synthesis of active ubiquitin: roles of E1 and E2 enzymes
Gene Ontology:
Molecular function: chromatin binding; protein binding; ubiquitin conjugating enzyme activity; ubiquitin protein ligase binding; ubiquitin-protein transferase activity; ubiquitin-like protein transferase activity
Biological process: DNA damage response; DNA repair; protein autoubiquitination; protein K11-linked ubiquitination; protein K27-linked ubiquitination; protein K29-linked ubiquitination; protein K48-linked ubiquitination; protein K6-linked ubiquitination; protein K63-linked ubiquitination; protein monoubiquitination; protein polyubiquitination; protein modification by small protein conjugation; protein ubiquitination
Cellular component: nucleus; nucleoplasm
Genetic constraint (gnomAD): Loss-of-function variants: 9 observed, 18.74 expected, observed/expected ratio (o/e) 0.48, 90% interval 0.29 to 0.84. The upper end of that interval is the gene's LOEUF score, 0.84, which puts it in group 3 of 6, group 1 being the genes least tolerant of losing a copy. Missense variants: 158 observed, 205.33 expected, observed/expected ratio (o/e) 0.77, 90% interval 0.68 to 0.88. Synonymous variants: 60 observed, 68.71 expected, observed/expected ratio (o/e) 0.87, 90% interval 0.71 to 1.08.
Homologues: Orthologues: chimpanzee UBE2T (99% identical), macaque UBE2T (96% identical), guinea pig UBE2T (90% identical), rabbit UBE2T (89% identical), mouse Ube2t (85% identical), pig UBE2T (83% identical), dog UBE2T (82% identical), rat Ube2t (82% identical), tropical clawed frog ube2t (66% identical), zebrafish ube2t (63% identical). Paralogues in human: UBE2N (34% identical), UBE2NL (31% identical), UBE2R2 (29% identical), CDC34 (28% identical), UBE2K (28% identical), UBE2C (28% identical), UBE2Z (27% identical), UBE2H (26% identical), UBE2B (26% identical), UBE2A (25% identical), UBE2G1 (25% identical), UBE2O (24% identical), and 12 more.
Diseases named in the same sentence as UBE2T in open-access papers:
UBE2T is named in the same sentence as 87 diseases in open-access papers, as found by Europe PMC text mining. Sharing a sentence is not in itself a finding about the gene and the disease. The quoted sentences say what the papers report.
Fanconi anemia (33 papers, 2012 to 2025). Fanconi anemia (FA) is a hereditary DNA repair disorder characterized by progressive pancytopenia with bone marrow failure, variable congenital malformations and predisposition to develop hematological or solid tumors. "Following a similar theme, monoubiquitylation of UBE2T at K86 (5 amino acids from the catalytic cysteine K91) is suggested to reduce E2 activity linked to the Fanconi anemia DNA repair pathway mediated by the E3 ubiquitin ligase FANCL." (PMID 35926457, 2022). "UBE2T depletion impairs DNA repair ability and causes chromosome abnormality, a feature of Fanconi anemia." (PMID 34461934, 2021). "Increased VWF has been implicated in vascular dysfunction and decreased UBE2T in Fanconi anemia, and acute deregulated expression of these genes may have contributed to the adverse outcomes observed within 2 weeks of Zeb1/2 deletion." (PMID 34550965, 2021). "UBE2T, located at 1q32.1, is an E2 protease and belongs to the Fanconi anemia (FA) signaling pathway in the Kyoto Encyclopedia of Genes and Genomes (KEGG) signaling pathway." (PMID 40259951, 2025). "Two genes in the HRR pathway, RAD51, and XRCC2, cell cycle regulation (CHEK2), and Fanconi Anemia (UBE2T) were significantly upregulated in Groups 3 and 4 (p = 0.042, p = 0.0042, p = 0.021, and p = 0.023, respectively)." (PMID 37334114, 2023). "Ubiquitin-conjugating enzyme E2T (UBE2T), also known as HSPC150, was initially identified as an important element in the Fanconi anemia (FA) pathway." (PMID 37373211, 2023). "UBE2T belongs to the family of ubiquitin-conjugating enzymes, which were initially identified as essential elements in the Fanconi anemia (FA) pathway." (PMID 37373211, 2023). "UBE2T is part of the Fanconi Anemia (FA) core complex and required for the activation of the FA pathway in DNA repair." (PMID 36293188, 2022). "UBE2T was initially identified as an E2 ubiquitin-conjugating enzyme in the Fanconi anemia pathway responsible for efficiently repairing damaged DNA." (PMID 34257599, 2021). "UBE2T was first identified in Fanconi Anemia (FA), which is responsible for DNA damage repair as a critical member of the FA pathway." (PMID 34257599, 2021). "Lastly, altered expression of Vwf (up) and Ube2t (down) genes that are involved in clotting/vascular disorders and Fanconi anemia, respectively, were also DEGs in Zeb1Δ/Δ LSKs." (PMID 34550965, 2021). "On the other hand, UBE2T is the E2 ubiquitin-conjugating enzyme for the Fanconi Anemia pathway and monoubiquitinates several proteins of the pathway, that also appeared in our screening like FANCD2 and FANCI." (PMID 33925616, 2021). "UBE2T is essential for the Fanconi anemia DNA repair pathway which has been newly connected to ribosome biogenesis." (PMID 32813698, 2020). "Here, we modeled an unusual somatic reversion event in a Fanconi anemia (FA) patient who had inherited a partial genomic duplication in the FANCT/UBE2T gene from his mother." (PMID 30715513, 2019). "Ubiquitin-conjugating enzyme E2T (UBE2T) is served to connect with particular E3 ubiquitin ligase to degraded-related substrates, contributing to DNA repair in the Fanconi anemia pathway." (PMID 30622320, 2019). "UBE2T is a ubiquitin ligase and a component of the Fanconi anemia pathway (FANCT, MIM 616,435)." (PMID 35486341, 2022). "Ubiquitin-conjugating enzyme E2T (UBE2T) is an essential E2 enzyme involved in the efficient repair of damaged DNA in the Fanconi anemia pathway, and the regulation of this pathway may involve a UBE2T self-inactivation mechanism." (PMID 36338541, 2022). "UBE2T was initially identified as an E2 in the Fanconi anemia (FA) pathway." (PMID 34461934, 2021).
Fanconi anemia (continued). "UBE2T was initially reported to be the ubiquitin-conjugating enzyme in the Fanconi anemia pathway and had a self-inactivation mechanism that could be essential for negative regulation of the Fanconi anemia pathway (Zhang, Zhou & Huang, 2007)." (PMID 32025379, 2020). "Additionally, we found that UBE2T inhibits DNA replication stress pathways and is essential for the Fanconi anemia pathway, which is involved in the maintenance of genome stability through DNA damage repair, replication fork stabilization, and the alleviation of oxidative and mitotic stress." (PMID 36338541, 2022). "Pathway analyses with the KEGG and REAC databases revealed a significant enrichment of the Fanconi anemia (FA) repair pathway, with notable genes such as BRIP1 (FANCJ), FANCI, FANCA, SLX4 (FANCP), UBE2T (FANCT), and C19orf40 (FAAP24)." (PMID 38896450, 2024). "UBE2T, also known as HSPC150 or Fanconi anemia T histone (FANCT), is initially identified as a key E2 enzyme in the Fanconi anemia (FA) pathway." (PMID 39791716, 2024). "CaMKIIδ9 promotes cardiomyopathy and cell death by phosphorylation of ubiquitin-conjugating enzyme E2T (UBE2T), an enzyme in the Fanconi anemia DNA repair pathway, which leads to degradation of UBE2T and thereby accumulation of DNA damage [72•]." (PMID 32789749, 2020). "Ubiquitin-conjugating enzyme E2T (UBE2T, also called HSPC150), a member of the E2 family, was initially found in a case of Fanconi anemia." (PMID 31128423, 2019). "The primary function of the UBE2T ubiquitin conjugase is in the monoubiquitination of the FANCI-FANCD2 heterodimer, a central step in the Fanconi anemia (FA) pathway." (PMID 30715513, 2019). "Despite the biological functions of UBE2T have ever been well studied in breast cancer and Fanconi anemia, none therapeutic inhibitors targeting UBE2T have been reported yet." (PMID 33323973, 2021). "Fanconi anemia (FA) is a recessive disorder caused by biallelic mutations in one of the (so far) nineteen FANC genes, of which only two (RAD51 and UBE2T) are not covered by the TruSight Cancer panel." (PMID 29659569, 2018).
hepatocellular carcinoma (33 papers, 2020 to 2025). A malignant tumor that arises from hepatocytes. "ANLN is associated with the progression of lung, pancreatic, and cervical cancers, whereas UBE2T is associated with proliferation in hepatocellular carcinoma, glioblastoma, gastric cancer, and renal cell carcinoma." (PMID 35578283, 2022). "Ubiquitin‐conjugating enzyme E2T (UBE2T) has been implicated in many types of cancer including hepatocellular carcinoma (HCC)." (PMID 34614271, 2022). "Consistently, overexpressed UBE2T was associated with poor prognosis in gastric cancer, hepatocellular carcinoma, osteosarcoma and breast cancer." (PMID 34838005, 2021). "UBE2T is associated with poor prognosis in hepatocellular carcinoma patients." (PMID 33934686, 2021). "A series of studies have shown that UBE2T is overexpressed as an oncogene in various types of cancer, including hepatocellular carcinoma, lung adenocarcinoma, pancreatic cancer, breast cancer, ovarian cancer, gastric cancer, and glioblastoma." (PMID 39791716, 2024). "In hepatocellular cancer, CASC11 associates with ubiquitin-conjugating enzyme E2T (UBE2T) mRNA and stabilizes it." (PMID 39280246, 2024). "In detail, LncRNA CASC11 is involved in the regulation of cell proliferation, migration as well as invasion through the upregulation of Ubiquitin-conjugating enzyme E2T (UBE2T) in an m6A-dependent manner in hepatocellular carcinoma." (PMID 37365581, 2023). "The latest research shows that ubiquitin-conjugating enzyme E2T(UBE2T) increases pyrimidine metabolism by promoting the ubiquitination of Akt Lys63 connection, thus contributing to the occurrence and development of hepatocellular carcinoma." (PMID 37190313, 2023). "Ubiquitin-conjugating enzyme E2T (UBE2T) has been considered as the pivotal target of lncRNA CASC11 to drive the malignant phenotype of hepatocellular carcinoma." (PMID 36875073, 2023). "It was also shown that UBE2T overexpression prevented hepatoma cell proliferation, colony formation, tumorigenesis, migration, and invasion, but UBE2T inhibition had the reverse effect." (PMID 36245987, 2022). "Previous studies have reported that UBE2T is overexpressed in several cancer types, such as melanoma, ovarian cancer, renal cancer and hepatocellular carcinoma, and its overexpression correlates with cancer progression and poor prognosis." (PMID 36338541, 2022). "The oncogene protein ubiquitin-conjugating enzyme E2T (UBE2T) is reported to be upregulated in hepatocellular carcinoma (HCC) and correlated with poor clinical outcomes of HCC patients." (PMID 35169125, 2022). "UBE2T has also been shown to be an oncogene in non-small cell lung cancer, renal cell carcinoma, and hepatocellular carcinoma." (PMID 34703898, 2021). "UBE2T is first identified in the hematopoietic stem cells and plays critical role in the maintaining of hepatocellular carcinoma stem cells." (PMID 34703898, 2021). "In accordance with the present results, previous studies have demonstrated that UBE2T was directly targeted and downregulated by miR-543, which attenuated the proliferation and progression of hepatocellular carcinoma." (PMID 34787051, 2021). "This work is aimed to probe the role of UBE2T in the progression of hepatocellular carcinoma (HCC) patients." (PMID 33934686, 2021). "Herein, our findings showed that both SENP1 and UBE2T were upregulated in either hepatoma cell lines or tumor tissues and their expression levels were positively related." (PMID 31969492, 2020).
hepatocellular carcinoma (continued). "UBE2T, functioning as an E2 enzyme, has been identified as a crucial regulator of tumor advancement in various types of cancer, including gastric cancer, hepatocellular carcinoma, pancreatic cancer, lung adenocarcinoma, retinoblastoma, and glioblastoma." (PMID 38656363, 2024). "Moreover, increasing evidence has shown that UBE2T is involved in the carcinogenesis of different types of tumors, including lung cancer, gastric cancer, hepatocellular carcinoma, nasopharyngeal, osteosarcoma, and prostate cancer." (PMID 34257599, 2021). "Previous studies have reported that UBE2T could affect critical cellular events in different types of cancer, including breast cancer, hepatocellular carcinoma, and multiple myeloma." (PMID 34257599, 2021). "miR-212-5p inhibits hepatocellular carcinoma progression via regulating UBE2T." (PMID 33934686, 2021). "UBE2T is generally aimed by miR-543, which is, however, low in hepatocellular carcinoma conditions." (PMID 34769401, 2021). "Moreover, miR-1305 was found to restrict the activation of the AKT signaling pathway by competitively binding UBE2T in order to suppress the tumorigenicity of hepatocellular carcinoma cells." (PMID 33292234, 2020). "The cooperative roles of SENP1 and UBE2T in development and progression of hepatocellular carcinoma (HCC) are still unknown." (PMID 31969492, 2020). "SENP1 regulates hepatocellular carcinoma (HCC) carcinogenesis through deSUMOylation of ubiquitin-conjugating enzyme E2T (UBE2T) and HIF1α." (PMID 34503213, 2021). "Therefore, a high level of UBE2T has been depicted in different kinds of cancer, including lung cancer, hepatocellular carcinoma, and renal cell carcinoma, suggesting the tumor-promoting role of UBE2T, which has the potential to act as a promising drug target in cancer therapy." (PMID 34787051, 2021). "Consistently, our analysis revealed the high expression of UBE2T in most hepatocellular carcinoma tissues and HCC cell lines." (PMID 31969492, 2020). "The role of these genes (UBE2T, CDCA3, and CDCA5) in the progression of hepatitis, cirrhosis and hepatocellular carcinoma remains to be further investigated." (PMID 38890649, 2024). "Interestingly, UBE2T plays an essential part in the DNA damage pathway, and it has been demonstrated to be correlated intimately with the development and poor prognosis of several cancers, such as gastric cancer, hepatocellular cancer, prostate cancer, and gallbladder cancer." (PMID 36910645, 2023). "In hepatocellular carcinoma (HCC), UBE2T desumoylation by SENP1 is related to carcinogenesis, which associates with upregulation of both proteins." (PMID 35887358, 2022). "SENP1-mediated deSUMOylation of UBE2T promotes HCC development through activation of the PI3K-AKT pathway, and both SENP1 and UBE2T are overexpressed in most HCC tissues and hepatoma cell lines." (PMID 34503213, 2021). "The study in hepatocellular carcinoma demonstrated that SENP1 deletion inhibited proliferation and induced cell cycle dysregulation through the deSUMOylation of ubiquitin conjugating enzyme E2 T (UBE2T)." (PMID 38389923, 2024). "Moreover, LncRNA CASC11 also interfered the interaction between UBE2T mRNA and YTHDF2, thereby influencing proliferation and metastasis of hepatocellular carcinoma cells." (PMID 37365581, 2023). "On the other hand, UBE2T also could mediate H2AX/γH2AX monoubiquitylation on facilitating cell cycle arrest activation to provide sufficient time for radiation-induced DNA repair, thus conferring hepatocellular carcinoma radio-resistance." (PMID 34838005, 2021).